PDX1 (pancreatic and duodenal homeobox 1)
Diseases named in the same sentence as PDX1 in open-access papers (continued):
Sharing a sentence is not in itself a finding about the gene and the disease.
Hyperglycemia (continued). "In addition, even unrescued groups of mice from hBMSCs-VEGF and hBMSCs-PDX1 with persistent hyperglycemia showed significantly higher levels of total serum insulin and number of endogenous β-cells compared with other groups resulting in overall better clinical outcomes." (PMID 22879915, 2012). "The inhibition of PDX-1 and EGFR signaling in the pancreas by chronic hyperglycemia results in impaired insulin synthesis and secretion and β-cell proliferation." (PMID 41189666, 2025). "A well-known combination of factors - Pdx1, Ngn3, and MafA (PNM) has been shown to convert exocrine cells into insulin-producing β-like cells, ameliorating hyperglycemia in mice." (PMID 41584842, 2025). "The effect was extended to the PP stage, with significantly lower expressions of PP markers (PDX1, NKX6−1 and NKX6−2) in the hyperglycemia-treated group than the control." (PMID 34639069, 2021). "Moreover, hyperglycemia increased ROS production by driving mitochondria toward increased oxygen use and decreased ATP formation, which in turn suppressed insulin generation in pancreatic β-cells by inhibiting insulin gene transcription factors such as Pdx1 or MafA63,64." (PMID 32439909, 2020). "To determine the potential effect of chronic hyperglycemia on AD-like pathophysiology, we generated an animal model by crossbreeding APP/PS1 and Pdx1+/− mice." (PMID 27406855, 2016). "To investigate the effects of hyperglycemia on Aβ deposition in APP/PS1 mouse brains, we compared the levels of SP and AβO between the Pdx1+/−/APP/PS1 and APP/PS1 mice." (PMID 27406855, 2016). "IPCs express the pancreatic β-cells developmental genes such as pancreatic and duodenal homeobox-1 (PDX-1) or functional genes such as insulin, and glucagon and secrete insulin in response to glucose that reverses hyperglycemia in drug-induced diabetic mice." (PMID 23648189, 2013). "The results indicated that the Pdx1 double allelic mutants, as opposed to heterozygous individuals, exhibited hyperglycaemia compared to the d/d controls." (PMID 39958891, 2025). "Gck activation substantially ameliorated hyperglycemia in pdx1 mutants, without inducing oxidative stress responses in liver or islet." (PMID 39580550, 2024). "In this regard, a direct contribution of an altered expression of transcription factors involved in the maintenance of β-cell identity (e.g. PDX1, NKX6.1, MAFA or NEUROG3, among others) has been proposed to explain β-cell failure under pathological conditions of hyperglycemia and lipotoxicity." (PMID 37274331, 2023). "Of note, our recent data also demonstrated that GSK-3β was not inhibited in Pdx1+/−/APP/PS1 mice, indicating that GSK-3β is not closely linked to chronic hyperglycemia-induced tau hyperphosphorylation." (PMID 28467789, 2017). "Therefore, we can infer that hyperglycemia exposure promoted the cerebral processing of APP during amyloidosis and attenuated Aβ clearance, which subsequently resulted in SP formation in the Pdx1+/−/APP/PS1 mouse brains." (PMID 27406855, 2016). "Sustained hyperglycaemia damages β cell function via several mechanisms such as an increase in oxidative stress, activation of the MAPK pathway, and reduction of the pancreatic and duodenal homeobox factor-1 (PDX-1) function." (PMID 26640807, 2016). "Indeed, mice deficient in PDPK1 in β cells manifest reduced β-cell numbers and hyperglycemia, while AKT overexpression under the Pdx1 promoter results in β-cell dedifferentiation." (PMID 25875172, 2015). "Despite a marked reduction in PDX1-positive cells, a substantial β-cell number remained in STZ-treated MIP-HSD1tg/+ islets, although the comparable hyperglycemia between genotypes from day 2 to 3 indicates these β-cells underwent a period of initial secretory dysfunction." (PMID 25352830, 2014). "Hyperglycemia induces activation of the c-Jun N-terminal kinase (JNK) pathway, which suppresses insulin gene expression and reduces DNA binding of pancreatic and duodenal homeobox factor (PDX)-1." (PMID 24422903, 2014).
Hyperglycemia (continued). "As a demonstration of Gck treatment responses in a whole-organism model, we showed that Gck activity can be modulated by the GKA Dorzagliatin to ameliorate hyperglycemia in pdx1 mutants, which occured without detectable activation of oxidative stress responses in liver or endocrine β-cells." (PMID 39580550, 2024). "Chronic hyperglycemia in IRS2-null mice may contribute to dedifferentiation via oxidative stress or glucotoxicity, but it is likely not the only cause, since Pdx1 expression is reduced before the onset of hyperglycemia." (PMID 37712417, 2023). "In addition, db/db mice with hyperglycemia had increased levels of pancreatic β-cell dedifferentiation independently of blood lipid levels; their pancreatic islets had decreased levels of mature β-cell markers such as GLUT2, Pdx-1, MafA and Nkx6.1." (PMID 33918379, 2021). "In order to determine whether Men1 ablation prevents STZ-induced hyperglycemia partly through its regulation on Pdx-1 and/or GLUT2, we sought to detect expression or localization of Pdx-1 and GLUT2 in beta cells in STZ-treated control and Men1-excised mice by immunostaining." (PMID 21318185, 2010). "In addition, a study showed that when the activity of the phosphoinositide 3-kinase (PI3K)/AKT/FoxO1/PDX-1 signaling pathway in islets was upregulated, PDX-1 was redistributed from the cytoplasm to the nucleus, and insulin secretion could be improved, thus ameliorating hyperglycemia." (PMID 36551213, 2022). "The injury response to chronic hyperglycemia characterized here is distinct in the apparent replacement of cones from the ‘rod progenitor’ cell population, as we observed neurod:GFP+ cones in the ONL of pdx1 mutants which were not seen in controls." (PMID 34831487, 2021).
type 2 diabetes (78 papers, 2005 to 2026). "Autoantibodies against Pdx1 have been detected in Type 1 diabetes, and mutations in Pdx1 are associated with increased Type 2 diabetes (T2D) risk." (PMID 40134803, 2025). "In humans, 5% of diagnosed type-2 diabetes patients present with genetic defects in PDX1 and mutations in PDX1 define a subset of maturity-onset diabetes of the young 4 (MODY 4)." (PMID 36187092, 2022). "PDX1 is also linked to both type 1 and type 2 diabetes pathogenesis; in type 1 diabetes (T1D) PDX1 autoantibodies have been detected." (PMID 36589234, 2022). "PDX1 plays an important role in pancreatic development and beta cell differentiation, and mutation in the PDX1 gene can cause maturity-onset diabetes in the young." (PMID 36225477, 2022). "In the context of human insulin-positive β cells isolated from type 2 diabetes patients, proximity ligation of PDX1 with Brg1:Swi/Snf showed that their association is impaired compared to cells isolated from healthy patients." (PMID 36272648, 2022). "One lncRNA, PLUTO, is downregulated in type 2 diabetes and controls PDX1, encoding a key β cell transcription factor." (PMID 28041957, 2017). "PDX-1 is the major transcriptional regulator in mature β-cells and mediates expression of key β-cell genes, with homozygous mutations linked to Type 2 Diabetes development." (PMID 28893192, 2017). "In this study, we used an extensive re-sequencing approach to test the role in Type 2 diabetes of a comprehensive set of low frequency and rare PDX1 variants." (PMID 21569088, 2011). "The aim of this study was to assess the role of low frequency PDX1 (also called IPF1) variants in Type 2 diabetes." (PMID 21569088, 2011). "MODY4 is a form of early onset type-II diabetes mellitus associated with a disruption in one allele of the Pdx1 or insulin promoter factor-1 (IPF1) gene." (PMID 20587063, 2010). "In addition, six novel PDX-1 missense mutations (C18R, D76N, R197H, Q59L, G212R and P2390) were identified in patients with type 2 diabetes." (PMID 36551213, 2022). "It is agreed that transcription factor Pdx-1 plays a critical role in regulating beta-cell function by activating genes essential for beta-cell identity; loss of beta-cell identity contributes to the pathogenesis of type 2 diabetes." (PMID 36093092, 2022). "Type 2 diabetes is associated with beta cell loss of identity, dedifferentiation or beta to alpha cell transdifferentiation, and can in later stages often result in loss of transcription factors such as MafA, Nkx6-1 and Pdx1." (PMID 34296320, 2021). "Beta cell failure is the main hallmark of type 2 diabetes and it has been reported that inactivation of pancreatic and duodenal homeobox 1 (encoded by Pdx1) in mature beta cells results in the loss of beta cell identity and a beta-to-alpha cell fate conversion in vivo." (PMID 34498099, 2021). "Moreover, heterozygous mutations in some of these genes, PDX1 and HNF1α, are also responsible for different monogenic forms of maturity onset diabetes of the young (MODY 4 and MODY 5)." (PMID 33101198, 2020). "Moreover, the decrease of MAFA, MAFB, and PDX1 expression levels have been found in human type 2 diabetes islet alpha and beta cells, which can be associated to islet cell dysfunction." (PMID 31405383, 2019). "Importantly, heterozygous mutations of the Pdx1 gene in humans are associated with maturity-onset diabetes of the young type 428." (PMID 27406855, 2016). "It is noted here, however, that dominant monogenic MODY4 mutations in the PDX-1 gene in humans are not necessarily equivalent to PDX-1 heterozygosity in mice or humans, because it has been reported that recessive mutations in the PDX-1 gene also lead to susceptibility to Type 2 diabetes in humans." (PMID 25794287, 2015). "Interestingly, reduced expression of the PDX-1 gene within the human pancreas has been linked with type 2 diabetes, a rare autosomal dominant form of type 2 diabetes called maturity onset diabetes of the young (MODY4) and pancreatic agenesis." (PMID 23882220, 2013).
type 2 diabetes (continued). "Furthermore, the PDX1 variant D76N has been widely studied, but the reproducibility of associations with Type 2 diabetes have varied." (PMID 21569088, 2011). "Mutations which affect the C-terminus of PDX1 are associated with the development of type 2 diabetes in humans, while other findings indicate that the C-terminal domain may serve as both repressor and activator of PDX1 function." (PMID 20637728, 2010). "In a study, a child’s pancreas did not develop (pancreatic agenesis) because the child was homozygous for an inactivating cytosine deletion in the protein-coding sequence of PDX-1 (pro63fsdelc), which indicated that PDX-1 might be associated with Type 2 diabetes." (PMID 36551213, 2022). "While FOXA2 has been shown to control mRNA levels of PDX1, HNF1A, and HNF4A, mutations in HNF1A, HNF1B, HNF4A, and PDX1 are known to cause maturity-onset diabetes of the young (MODY)." (PMID 39322760, 2024). "There was enrichment in the pathways involved in beta-cell development (P = 0.02) and maturity onset diabetes of the young (P = 0.02) due to the inclusion of PDX1 and HNF4G." (PMID 39002386, 2024). "The significance of transcription factors such as PDX1/IPF1 (MODY4) and NeuroD1 (MODY6) in pancreatic development was further reinforced by the analysis of mutations in patients with maturity-onset diabetes of the young (MODY)." (PMID 37175791, 2023). "Although some previous studies have reported decreased expression levels of MafA and PDX1 in type 2 diabetes, the present study showed increased expression levels of both factors in STZ-diabetic rats." (PMID 36109786, 2022). "In aging animal models of type 2 diabetes, the expression of the PDX-1 gene was decreased, the number of β cells was reduced, and the long-term use of GLP-1 reversed these pathological changes." (PMID 36551213, 2022). "Variants in four maturity-onset diabetes of the young (MODY) genes and the PDX1 gene have also been implicated in GDM development." (PMID 36992779, 2022). "Pancreatic β-cell-specific PDX1 deficiency in mice leads to the reduced expression of insulin and SLC2A2, causing maturity-onset diabetes." (PMID 36361703, 2022). "Acarbose ameliorates spontaneous type-2 diabetes in db/db mice by promoting the proliferation of islet β cells and inhibiting PDX-1 methylation." (PMID 36551213, 2022). "One of the major mechanisms for beta-cell dysfunction in type-2 diabetes results from oxidative stress-dependent inhibition of PDX1 levels and function." (PMID 36187092, 2022). "One of the major mechanisms for beta-cell dysfunction in type-2 diabetes involves the inhibition of Pdx1 by oxidative stress." (PMID 36187092, 2022). "Among these effector genes are ABCC8, KCNJ11, PDX1, ADCY5, and KCNQ1, which are recognized as pancreatic β-cell genes strongly associated with type 2 diabetes." (PMID 34425882, 2021). "IGF2BP2 also directly binds to PDX1 in an m6A-dependent manner and promotes pancreatic β-cell proliferation in type 2 diabetes." (PMID 35047491, 2021). "This systematic review provides an overview of ZIP transcript expression in the context of β-cell specificity, cytokine stimulation, PDX-1 activity, glucose status and Type 2 Diabetes." (PMID 28893192, 2017). "Our observations suggest that hepcidin is associated with gluco-toxicity-reduced pancreatic β-cell insulin synthesis in type 2 diabetes by inhibiting Pdx-1 expression." (PMID 28179377, 2017). "We sequenced the coding and flanking intronic regions of PDX1 in 910 patients with Type 2 diabetes and 878 control subjects." (PMID 21569088, 2011). "For instance, deletion of a type 2 diabetes-associated enhancer within the ONECUT1 locus reduced the number of one cut homeobox 1 (ONECUT1)- and pancreatic and duodenal homeobox 1 (PDX1)-positive pancreatic progenitors, implicating this element in early beta cell differentiation." (PMID 40768044, 2025).
type 2 diabetes (continued). "Pdx1 is a transcription factor that is involved mainly in the formation of β cells, and a decrease in its expression leads to functional alterations in pancreatic insulin secretion and the development of type 2 diabetes in humans." (PMID 38673723, 2024). "Previous studies have demonstrated that the genetic and acquired reduction in the expression of PDX1 may lead to type 2 diabetes and β-cell dysfunction." (PMID 31322178, 2019). "We therefore hypothesised that PDX1 and other transcription factors in the network regulate the differentially expressed genes in type 2 diabetes." (PMID 29185012, 2018). "We further demonstrate that the lncRNA PLUTO affects local 3D chromatin structure and transcription of PDX1, encoding a key β cell transcription factor, and that both PLUTO and PDX1 are downregulated in islets from donors with type 2 diabetes or impaired glucose tolerance." (PMID 28041957, 2017). "Finally, we show that PLUTO and PDX1 are downregulated in islets from organ donors with type 2 diabetes or impaired glucose tolerance, suggesting a potential role in human diabetes." (PMID 28041957, 2017). "Indeed, heterozygous mutation of PDX-1 causes glucose intolerance, associated with increased islet apoptosis and impaired GSIS, which collectively results in maturity onset diabetes." (PMID 26167511, 2015). "Moreover, PDX-1 is required in adult humans to promote normal glucose sensing and insulin secretion, and mutations in PDX-1 represent a risk factor for type 2 diabetes." (PMID 26082830, 2015). "While it is well established that Pdx1 (also known as maturity onset diabetes of the young [MODY] 4) is required for MPC specification as well as for proper adult islet function, Pdx1 has also recently been shown to regulate Ngn3 directly in cooperation with Hnf6." (PMID 21829703, 2011). "However, epigenetic modifications of PDX1 reducing its activity could contribute to the development of type 2 diabetes since this transcription factor binds to the promoter of a large set of genes related to β-cell survival as well as insulin secretion." (PMID 31682591, 2020). "While in type 2 diabetes (T2D), PDX1 expression levels are compromised." (PMID 36589234, 2022). "They suggested that dysregulation of PDX-1 by genetic or functional mechanisms might be a common element in autosomal early-onset (MODY) and common type 2 diabetes." (PMID 26082830, 2015). "Moreover, SIRT5 may regulate the transcription of pancreatic and duodenal homeobox 1 (PDX1) via H4K16 deacetylation, to participate in pancreatic β−cell proliferation and insulin secretion in type II diabetes." (PMID 39372420, 2024). "Some studies also found that following the overexpression of the PDX-1 gene in islets, insulin secretion, and glucose tolerance were enhanced, and the expression of MafA and GCK genes, which maintain normal β-cell function, were restored in maturity-onset diabetes of the young (MODY) mice." (PMID 36551213, 2022). "Systems biology approaches identified HNF1A, PDX1 and REST as drivers of gene co-expression modules correlated with impaired insulin secretion or glucose tolerance, and 14 out of 19 differentially expressed type 2 diabetic islet signature genes were enriched in these modules." (PMID 29185012, 2018).